TMPRSS2 (transmembrane serine protease 2)
Diseases named in the same sentence as TMPRSS2 in open-access papers (continued):
Sharing a sentence is not in itself a finding about the gene and the disease.
COVID-19 (continued). "On stepwise regression, TMPRSS2/ACE2 ratio outperformed ACE2 to model COVID-19 severity." (PMID 33958627, 2021). "Notably, we discovered the age-related expression of ACE2 and TMPRSS2 in the immune-inflammatory stromal cells, implying the potential interplay between COVID-19, stromal cells, and aging." (PMID 34094637, 2021). "Given that furin and TMPRSS2 are both proteinases and ACE2 was reported as the main viral receptor for COVID-19, comparison between OS and TMPRSS2, ACE2 and furin was conducted and found that only KIRC and LGG show the same patterns of OS, demonstrating their ubiquity in different cancers." (PMID 34671211, 2021). "Association between AKI in COVID-19 and urinary SARS-CoV-2 N, ACE2, and TMPRSS2." (PMID 34113632, 2021). "From March 11, 2020 to October 31, 2020, we enrolled and studied 239 SARS-CoV-2-positive and 253 SARS-CoV-2-negative patients to determine associations of the SNPs rs2070788, rs383510, and rs12329760 in the gene TMPRSS2 with susceptibility to SARS-CoV-2 infection and severity of COVID-19." (PMID 33968142, 2021). "High level of NRP1 in lung cancer tissues is associated with poor survival, making it a potential therapeutic target in COVID-19 patients with lung cancer, while high level of TMPRSS2 correlates with better prognosis, excluding the attempt of targeting TMPRSS2 in comorbidity." (PMID 34168096, 2021). "The expression of ACE2/TMPRSS2 in the mucosa of the pharynx and larynx may explain the involvement of mild oral and throat symptoms in patients with COVID-19." (PMID 34445619, 2021). "Moreover, TMPRSS2 is involved in the cleavage of the spike protein of SARS-CoV-2, and a TMPRSS2 inhibitor has been described that can block cell entry of the virus, representing a possible therapeutic strategy for the treatment of COVID-19." (PMID 34072295, 2021). "IHC showed that both ACE2 and TMPRSS2 antigens could be observed in the spleens and LNs from COVID-19 autopsies." (PMID 33995382, 2021). "Meanwhile, camostat mesylate, a TMPRSS2 inhibitor, could block SARS-CoV-2 infection of lung cells, indicating that TMPRSS2 inhibitors might be a potential strategy for the treatment of COVID-19." (PMID 33987176, 2021). "Moreover, several studies suggested that the blocking of androgen signaling and the down-regulation of ACE2 and TMPRSS2 are protective against COVID-19." (PMID 33401657, 2021). "Therefore, elucidating the underlying genetic regulatory mechanisms of TMPRSS2 and ACE2 co-expression will help to inform the prevention and treatment of GI disorders in COVID-19 patients." (PMID 34834564, 2021). "Previous studies have suggested that different host ACE2 and TMPRSS2 genetic backgrounds might contribute to differences in the rate of SARS-CoV-2 infection or COVID-19 severity." (PMID 33824725, 2021). "It is important to note that ACE2 and TMPRSS2 were not directly listed in DisGeNET as genes associated with COVID-19." (PMID 33055059, 2020). "Future clinical studies need to be performed in COVID-19 patients including newly infected subjects and patients with severe pathogenesis, to elucidate the role of hypokalemia in increasing TMPRSS2 expression, which contributes to SARS-CoV-2 propagation and osmotic crisis." (PMID 33142989, 2020). "Angiotensin-converting enzyme 2 (ACE2) and serine protease TMPRSS2 have been implicated in cell entry for severe acute respiratory syndrome coronavirus 2 (SARS-CoV-2), the virus responsible for coronavirus disease 2019 (COVID-19)." (PMID 33391794, 2020). "Materials and Methods: Clinical exome data of 103 individuals was analyzed to identify sequence variants in five selected candidate genes: ACE2, TMPRSS2, CD209, IFITM3, and MUC5B to assess their prevalence and role to understand the COVID-19 infectivity and progression in our population." (PMID 33101356, 2020). "Apart from finding co-expression of ACE-2 and TMPRSS2 in sperm cells, there would seem to be evidence that COVID-19 could indirectly affect male fertility." (PMID 33312128, 2020).
COVID-19 (continued). "Notably, SERPINA1/alpha-1 antitrypsin was shown to inhibit TMPRSS2 in an enzymatic assay and is suggested as an antiviral treatment for COVID-19." (PMID 33143316, 2020). "Recent studies suggest that COVID-19 may cause acute renal failure, as both podocytes and proximal convoluted tubular cells express certain genes (ACE-2 and transmembrane serine protease 2 [TMPRSS2]) that increase the host viability for SARS-CoV-2." (PMID 32837414, 2020). "Taken together, our findings indicate that TMPRSS2 represents a valid target in COVID-19 treatment, which may be achieved by specific non-coding-RNA approaches." (PMID 33143053, 2020). "Sex, age, body mass index (BMI), and CKD are clinical risk factors for COVID-19 severity, but the relationships between kidney ACE2 and TMPRSS2 expression and these clinical variables are unknown." (PMID 33125431, 2020). "The anticipated impact of SARS-CoV-2 intercepting ACE2, TMPRSS2, and ENaC could provide a mechanistic cue to severe anxiety and increase in suicidal tendencies in COVID-19 patients, which are commonly attributed to isolation during hospitalization." (PMID 33142989, 2020). "Development of novel approaches for regulating the expression of angiotensin-converting enzyme 2 (ACE2) and transmembrane serine protease 2 (TMPRSS2) is becoming increasingly important within the context of the ongoing COVID-19 pandemic since these enzymes play a crucial role in cell infection." (PMID 32726325, 2020). "Transmembrane serine protease 2 (TMPRSS2) knockout mice may also be useful for investigating COVID-19 pathogenesis because TMPRSS2 is involved in cellular SARS-CoV-2 entry." (PMID 32793245, 2020). "That expression of TMPRSS2 is dependent on androgen (AR) expression, however, may explain why human males appear to show significantly higher mortality with COVID-19." (PMID 32574196, 2020). "Thus, aprotinin is an inhibitor of TMPRSS2 worthy of consideration for further testing and possible development as a therapeutic treatment for COVID-19." (PMID 32703818, 2020). "Since these effects in the RAAS and TMPRSS2 may potentialize SARS-CoV-2 infectivity and increase risk of thromboembolic events, aromatase inhibitors should be discouraged as candidates for COVID-19." (PMID 32993622, 2020). "The importance of TMPRSS2 is highlighted as the authors showed that a clinically approved TMPRSS2 inhibitor could effectively inhibit viral entry, opening the door for expedited clinical testing in COVID-19 patients." (PMID 32961074, 2020). "Our study suggests low incidence of maternal viremia and nonoverlapping placental ACE2 and TMPRSS2 expression as potential mechanisms associated with protection against placental infection and vertical transmission in maternal COVID-19." (PMID 33351086, 2020). "It has been shown that African Americans and the elderly present increased levels of TMPRSS2, which might to some extent explain the increased severity of COVID-19 seen in these two populations." (PMID 33519802, 2020). "In summary, ACE2 and TMPRSS2 gene networks contained genes that could contribute to the pathophysiology of COVID-19." (PMID 33318519, 2020). "While host machinery, including ACE2 and TMPRSS2, supports the similar entrance, inflammation, and hypoxia across coronavirus infections, neurological manifestations in sensory and nervous tissues are distinct in COVID-19." (PMID 33142989, 2020). "Therefore, in this review, we focus on the main pathophysiological aspects of ACE2, ADAM17, and TMPRSS2 host proteins in COVID-19." (PMID 33117379, 2020). "It follows that the expression of ACE2 and TMPRSS2 in the lung epithelium might have implications for the risk of SARS-CoV-2 infection and severity of COVID-19." (PMID 33391794, 2020). "Thus, TMPRSS2 is potentially the most promising target for COVID-19 therapy, based on its specific expression in lung, its important role in the process of cell infection, and its interactions with other proteins involved in the infection process." (PMID 33375616, 2020).
COVID-19 (continued). "Testosterone can increase the expression of ACE2 and TMPRSS2, and apart from human immune response, lifestyle differences and other factors affect the progress and prognosis of COVID-19, providing a possible explanation for the male-dominated infection and higher mortality." (PMID 33330557, 2020). "As such, this paper focuses on the potential role of BPA in promoting comorbidities associated with severe COVID-19, as well as on potential BPA-induced effects on key SARS-CoV-2 infection mediators, such as angiotensin-converting enzyme 2 (ACE2) and transmembrane serine protease 2 (TMPRSS2)." (PMID 33066495, 2020). "Moreover, the high risk of infection of neonates implied by the highest expression level of ACE2 and TMPRSS2 suggests that neonates should get the COVID-19 vaccine as soon as they were born if the vaccines are available." (PMID 33537060, 2020). "The potential clinical utility of AAT treatment in COVID-19 patients is based on the following considerations: (i) AAT acts as an efficient inhibitor of the host transmembrane protease serine 2 (TMPRSS2) protein receptor, which is essential during the initial phase of the SARS-CoV-2 infection." (PMID 33195215, 2020). "Hence, we searched for possible genetic components of COVID-19 severity among Italians by looking at expression levels and variants in ACE2 and TMPRSS2 genes, crucial for viral infection." (PMID 32501810, 2020). "The lower expression of ACE2 and TMPRSS2 with inhaled corticosteroid use warrants prospective study of inhaled corticosteroid use as a predictor of decreased susceptibility to SARS-CoV-2 infection and decreased COVID-19 morbidity." (PMID 33101356, 2020). "The involvement of TMPRSS2 in viral S protein priming might explain, at least in part, the higher case fatality seen in males affected by COVID-19." (PMID 32450906, 2020). "The expression of ACE2 and TMPRSS2 in the lung epithelium might have implications for the risk of SARS-CoV-2 infection and severity of COVID-19." (PMID 33391794, 2020). "The therapeutic approaches against ACE2-mediated COVID-19 may involve: i) Vaccine production based on the spike S protein, ii) inhibition of virus and host cell fusion via transmembrane protease serine 2 (TMPRSS2) and iii) blocking ACE2 receptor." (PMID 32782493, 2020). "Additionally, we discuss a possible mechanism to explain the deleterious effect of ADAM17 and TMPRSS2 over-activation in the COVID-19 outcome." (PMID 33117379, 2020). "TMPRSS2 activity is modulated by androgens, which may justify why males are overrepresented among severe COVID-19 infected patients." (PMID 32850920, 2020). "It is worth mentioning that some studies and recent preprints have also reported ACE2 expression profiles in the human lung, while our study aims at having a more systematic assessment that includes not only ACE2 but also TMPRSS2, a newly confirmed protein required for COVID-19 entry." (PMID 32973879, 2020). "Hence, the use of AR antagonists to regulate TMPRSS2 expression for COVID-19 warrants further research." (PMID 32948238, 2020). "A deep learning-based drug–target interaction model predicts that certain anti-hepatitis C virus (HCV) medicines, like ombitasvir, daclatasvir, and paritaprevir, have a substantial affinity for TMPRSS2 and could potentially be repurposed for COVID-19 treatment." (PMID 40297833, 2025). "Therefore, the current study aimed to investigate if the DNA methylation levels of the ACE2 promoter are different depending on the genotype of five COVID-19-related polymorphisms: ACE2 rs2285666 and rs2074192, TMPRSS2 rs12329760 and rs2070788, and ACE1 rs1799752." (PMID 40076720, 2025). "Given the importance of intestinal ACE2 in regulating inflammation and glucose transport, we hypothesised that changes in ACE2 and TMPRSS2 due to low-grade inflammation and hyperglycaemia potentially contribute to severe disease development in COVID-19 patients with diabetes." (PMID 40227199, 2025).
COVID-19 (continued). "We screened 12 phytochemicals alongside 10 pharmaceuticals and three plant extracts, selected for known or hypothesised effects on the SARS-CoV-2 receptors and COVID-19 risk, for their effects on the expression of ACE2 or TMPRSS2 in differentiated Caco-2/TC7 human intestinal epithelial cells." (PMID 40227199, 2025). "Moreover, NM potently inhibits the activity of transmembrane serine protease 2 (TMPRSS2), thereby impeding the binding of SARS-CoV-2 to angiotensin-converting enzyme 2 (ACE2), a pivotal mechanism underlying its therapeutic efficacy against COVID-19." (PMID 40444038, 2025). "Transplacental transmission of COVID-19 can occur due to the low levels of SARS-CoV-2 viremia and the decreased co-expression of angiotensin converting enzyme 2 (ACE2) and trans-membrane protease serine 2 (TMPRSS2) required for the entry of SARS-CoV-2 into placental cells." (PMID 40006963, 2025). "The highest probability of developing moderate and severe clinical courses of COVID-19 among residents of Central Ukraine was found in G-allele carriers (especially the GG genotype) of the FGB gene (rs1800790) and carriers of the T-allele TMPRSS2 gene (rs12329760)." (PMID 40573382, 2025). "Furthermore, combination therapies are worth investigating since combining TMPRSS2 inhibitors with other antiviral medications may produce synergistic effects, increasing treatment outcomes for COVID-19 and other viral infections." (PMID 40297833, 2025). "The clinical relevance is reinforced by findings indicating that symptomatic COVID-19 patients exhibit higher TMPRSS2 expression levels than asymptomatic individuals, suggesting that targeting this protease could be particularly beneficial in treatment strategies aimed at symptomatic patients." (PMID 40297833, 2025). "In this context, ACE2 levels among cancer subtypes may influence COVID-19 susceptibility, and bioinformatic data showed an increased level of mRNA expression of both ACE2 and TMPRSS2 in colorectal and lung cancers, which were found to be more susceptible to COVID-19." (PMID 40361463, 2025). "Therefore, polymorphisms of transmembrane protease serine 2 (TMPRSS2) and serpine family E member 1 (SERPINE1) could help to elucidate the contribution of variability to COVID-19 outcomes." (PMID 38601158, 2024). "By examining the importance of the TMPRSS2 gene in the SARS-CoV-2 infection process, the incidence, and severity of COVID-19 may be directly related to the increased expression of the TMPRSS2 gene, potentially leading to diverse consequences for disease susceptibility in different communities." (PMID 39188881, 2024). "Also, earlier research done in Germany and Indonesia failed to discover any correlation between this TMPRSS2 gene variant and the severity of COVID-19." (PMID 38263160, 2024). "Thus, low TMPRSS2 expression levels may represent a protective factor against the development of COVID-19 symptoms and the infection itself." (PMID 38606293, 2024). "In addition, ACE2 and TMPRSS2 were expressed at higher levels in the taste buds of patients with COVID-19 than in the control group, indicating that SARS-CoV-2 infection might change the relative receptor expression." (PMID 38975331, 2024). "Given the critical participation of TMPRSS2 and SERPINE1 in SARS-CoV-2 infection, it is relevant to investigate whether their genetic variants could be associated with the severity of clinical manifestations and/or fatal outcomes in COVID-19 patients." (PMID 38601158, 2024). "In response to the recent COVID-19 pandemic, the search for therapeutic targets to combat the severity and complications of infection caused by SARS-CoV-2 has led to the identification of SERPINE1 as a natural inhibitor of the TMPRSS2 protease that enhances the viral infection process." (PMID 38601158, 2024).
COVID-19 (continued). "Despite several studies investigating different SNVs in genes such as TMPRSS2, ACE1, ACE2, and others with COVID-19 susceptibility, it remains unclear whether the CD147 rs8259T>A variant confers susceptibility to this infectious disease in the Mexican population." (PMID 37630479, 2023). "In addition to its anticoagulant effect and its ability to augment AAT inhibition of TMPRSS2, heparin may antagonize COVID-19 by other means." (PMID 37294003, 2023). "In addition, the androgen-independent expression of TMPRSS2 may contribute to the high prevalence of COVID-19 in males." (PMID 37371774, 2023). "An exonic mutation in TMPRSS2, an indel in ACE1, a mucus-oversecreting MUC5B variant, some HLA class 1 alleles and blood group O (possibly by lowering the risk of cardiovascular complications) may have a protective effect against severe COVID-19." (PMID 36680215, 2023). "Furthermore, it has been shown that TMPRSS2 is reduced in COVID-19 patients." (PMID 36830955, 2023). "Therefore, considering previous observations and the strong evidence of the involvement of the vascular system in the pathology of COVID-19, we examined the gene expression concentrations of ACE2 and TMPRSS2 and the susceptibility of different lung vascular cell types to SARS-CoV-2 infection." (PMID 37071849, 2023). "Also, these findings may suggest we should pay more attention to LUAD patients, especially those infected with COVID-19, who should avoid medicating TMPRSS2 inhibitors, such as ginsenosides to gain prophylactic and therapeutic benefits against COVID-19." (PMID 36992839, 2023). "Thus, androgen deficiency and testosterone dysregulation could modulate ACE2 and TMPRSS2 expression, further influencing COVID-19 outcomes in PLWH." (PMID 37243203, 2023). "Therefore, it is anticipated that future efforts in designing TMPRSS2 inhibitors may yield more effective inhibitors that can be used as anti-COVID-19 therapeutics targeting TMPRSS2." (PMID 38033388, 2023). "Indeed it was proposed that androgens may play a role in COVID-19 pathogenesis through the androgen-regulated transmembrane protease, serine 2 (TMPRSS2), which also plays a critical role in SARS-CoV-2-host cell membrane fusion." (PMID 37761791, 2023). "Moreover, our results identify TMPRSS2 as a promising drug target, with a potential role for camostat mesilate, a drug approved for the treatment of chronic pancreatitis and postoperative reflux esophagitis, in the treatment of COVID-19." (PMID 35104687, 2022). "Finally, COVID-19 patients with hyperglycemia also showed an increased expression of TMPRSS2." (PMID 35329890, 2022). "Genotyping of the TMPRSS2 rs12329760 variant on large COVID19 cohorts of patients of non-European genetic ancestry is, therefore, needed to assess its role in determining the differences in the severity of COVID-19 across various populations (e.g. between East Asia and Europe)." (PMID 35104687, 2022). "Thus, inhalation could be a safer way to administer protease inhibitors against COVID-19, tailored to reach TMPRSS2 that is expressed on the cell surface of target cells in the airways." (PMID 35871159, 2022). "Consequently, targeting the metalloproteinase pathway in addition to the TMPRSS2 and cathepsin-B/L pathways could be an effective strategy to cure COVID-19." (PMID 35708281, 2022). "Hence, TMPRSS2 inhibitors have been proposed as a potential drug target for COVID-19 therapy." (PMID 35871712, 2022). "Therefore, the results indicate that nafamostat has anti-inflammatory actions, beyond its ability to inhibit TMPRSS2, that might potentiate its anti-viral actions in pathologies such as COVID-19." (PMID 34991643, 2022). "The TMPRSS2 rs75603675 genotype (OR = 0.586), dyslipidemia (OR = 2.289), sex (OR = 0.586), and the Charlson Comorbidity Index (OR = 1.126) were identified as the main predictors of COVID-19 severity in 817 patients who attended Hospital Universitario de La Princesa during March and April 2020." (PMID 35636966, 2022).